EGFR (epidermal growth factor receptor)
Diseases named in the same sentence as EGFR in open-access papers (continued):
Sharing a sentence is not in itself a finding about the gene and the disease.
cervical carcinoma (continued). "Strategies towards EGFR inhibition in advanced and recurrent cervical cancers by either anti-EGFR antibodies (cetuximab) or by small molecule tyrosine kinase inhibitors (gefitinib, erlotinib, and lapatinib) are ongoing but have not yet been conclusive." (PMID 22091418, 2011). "Between MoAb directed against EGFR, the ones that are currently studied in cervical cancer patients are cetuximab and matuzumab." (PMID 22235224, 2011). "A classical randomized trial design is ideal if the biological target is well defined and present in the majority of the patient population, which appears to be the case for EGFR pathway activation or angiogenesis in cervical cancer." (PMID 22091418, 2011). "EGFR is overexpressed in more than half of all cervical cancers and its phosphorylated form is a dominant feature in 20%, suggesting that receptor EGFR blockage remains a promising target." (PMID 22091418, 2011). "A number of molecular markers have been proposed as prognostic determinants in cervical cancer, including the epidermal growth factor receptor (EGFR) family." (PMID 21730982, 2011). "To investigate the possibility that cervical cancer cells in which the EGFR gene was amplified or the protein overexpressed depended on EGFR signals for survival, we analysed cervical cancer cell lines for expression levels of EGFR by western blotting." (PMID 21730982, 2011). "In contrast, however, inhibition of EGFR in cervical carcinoma cells by the small molecule inhibitor PD153035 led to a dose-dependent increase in NFκB activation." (PMID 21203561, 2010). "Ongoing clinical studies in cervical cancer in which EGFR inhibition is combined with RT will evaluate if such treatment combination will increase radiosensitivity and if it involves inhibition of DNA-PK." (PMID 19672258, 2009). "Several clinical trials are evaluating the efficacy of anti-EGFR therapies for advanced cervical cancer." (PMID 19563658, 2009). "We and others have shown that in adenosquamous carcinoma EGFR overexpression varies from 33–43% of cases, being in the range of overall cervical cancer." (PMID 19563658, 2009). "Overexpression of EGFR has been reported to be frequent in cervical cancer, ranging from approximately 25–70%." (PMID 19563658, 2009). "From our results, it seems that EGFR expression is stable when comparing the lymph node metastases with the primary cervical cancers, which is surprising in the light of the genomic instability that characterizes most malignant tumors." (PMID 18700025, 2008). "Previous studies have shown EGFR to be frequently expressed in primary cervical cancer, and that EGFR expression is correlated with poor prognosis." (PMID 18700025, 2008). "The presence of EGFR and HER2 receptors have been associated with accelerated tumor progression and therapeutic resistance for several types of malignancies, including cervical cancer." (PMID 18700025, 2008). "The EGFR expression seems to be common and stable during cervical cancer metastasis, which is encouraging for testing of EGFR targeted radiotherapy." (PMID 18700025, 2008). "Blockade of EGFR in cervical cancer cell lines induces increased expression of genes that stimulate apoptosis and suppresses experimental metastasis." (PMID 17242701, 2007). "Epidermal growth factor receptor expression is higher in cervical intraepithelial neoplasia and cervical cancers than in normal controls." (PMID 16721365, 2006). "Our results demonstrate the essential role for EGFR in AP-1 activation when analyzed using an ME180 cervical cancer cell line." (PMID 16202132, 2005). "The expression of EGFR is elevated in cervical carcinoma cells." (PMID 41463185, 2025). "EGFR is highly expressed in cervical cancer tissues and cells." (PMID 40309242, 2025). "Yet, EGFR-TKIs are known for variable efficacy across cervical cancer subtypes, and compensatory cytokine pathways may limit long-term effects." (PMID 41373619, 2025).
cervical carcinoma (continued). "Finally, hsa-miR-2861 functions as a tumor suppressor by targeting the EGFR/AKT2/CCND1 pathway in human papillomavirus type 16 E6-induced cervical cancer." (PMID 41496911, 2025). "Similarly, our group previously observed that Erlotinib‐mediated EGFR inhibition increased RKIP expression in cervical cancer cells." (PMID 40720248, 2025). "Blocking EGFR signal transduction can increase tumor sensitivity to radiotherapy and chemotherapy, emphasizing the significance of EGFR as a target gene in the therapeutic approach to cervical carcinoma." (PMID 41463185, 2025). "Thus, our findings suggest that naringenin has therapeutic impacts on cervical cancer via multiple mechanisms, primarily by inhibiting the migration and invasion through the EGFR/PI3K/AKT/mTOR pathway." (PMID 38253629, 2024). "Additionally, the role of AFAP1-AS1/miR-7-5p/EGFR axis in gemcitabine tolerance remains to be investigated in animal model of cervical cancer." (PMID 39574469, 2024). "Importantly, the mechanism by which GPER can inhibit cervical cancer cell proliferation in vitro involves sustained activation of the ERK1/2 pathway through EGFR." (PMID 39409923, 2024). "In addition, the knockdown of EGFR attenuated the promoting effect of AFAP1-AS1 on cervical cancer development and gemcitabine tolerance." (PMID 39574469, 2024). "Similarly, MUC1 induced the resistance of both lung and cervical cancer cell lines to paclitaxel by upregulating ABCB1 in an EGFR-dependent manner." (PMID 38254882, 2024). "Furthermore, epidermal growth factor receptor (EGFR) expression was relevant to the accelerative effects of AFAP1-AS1 in cervical cancer by serving as a molecular sponge for miR-7-5p." (PMID 39574469, 2024). "Furthermore, most studies have focused on the use of EGFR inhibitors in combination with other treatments, such as chemotherapy or radiation therapy, and only a very few studies have investigated the use of EGFR inhibitors as a monotherapy in cervical cancer." (PMID 37310466, 2023). "Higher expression of EGFR/TGFBR1 has been shown to promote cervical cancer." (PMID 37894282, 2023). "Additionally, the alteration in the E6/E7 protein of HPV interferes with cervical cancer cell proliferation by decreasing EGFR stability at the posttranscriptional level." (PMID 37020674, 2023). "The data presented in this study are supportive that EGFR status could be used to identify cervical cancer patients who may be eligible for anti-EGFR therapies." (PMID 38414930, 2023). "In addition, EGFR signaling is a key component driving the initiation and progression of cervical cancer." (PMID 37020674, 2023). "Screening for EGFR should be considered in cervical cancer patients." (PMID 38414930, 2023). "Therefore, it is important to identify the cause of EGFR hyperactivation to overcome the clinical limitations of cisplatin treatment in cervical cancer patient with hyperactivated EGFR signaling." (PMID 37165076, 2023). "Larger prospective studies may better investigate the relationship between EGFR and survival in cervical cancer patients in Nigeria." (PMID 38414930, 2023). "CircMYBL2 governed paclitaxel resistance via targeting miR-665/EGFR axis in cervical cancer." (PMID 36438563, 2022). "Dysregulation and sustained activation of several RTKs, including VEGFR, HER2/ErbB2, MET, EGFR, and PDGFR, as well as its downstream oncogenic cascades can lead to cervical cancer tumorigenesis, which are associated with poor prognosis and chemoresistance for cervical cancer." (PMID 39282148, 2022). "In fact, E5 oncoprotein also induces phosphorylation of STAT in cervical cancer cells and may be regulated by activated EGFR." (PMID 35645817, 2022).
cervical carcinoma (continued). "EGFR activating mutations are not present in cervical carcinomas, so that induction of the gene by epigenetic pathways seems a plausible approach to increasing its activity in such carcinomas." (PMID 35008200, 2021). "As upstream modulators of COX-2, members of the mitogen-activated protein kinase (MAPK), extracellular-signal regulated kinase (ERK) family and EGFR may be indicators of outcome and survival in cervical cancer." (PMID 34830902, 2021). "Therefore, we propose uPA as a potentially novel candidate to be studied in combination with EGFR in cervical cancer, either as a therapeutic target or as a biomarker for EGFR signaling and patient prognosis." (PMID 33886813, 2021). "One such pathway is the EGFR pathway that is normally upregulated in cervical cancers." (PMID 35008200, 2021). "Furthermore, cervical cancer patients with increased expression of EGFR (P=0.023), uPA (P=0.0005), or TM (P=0.059) had decreased overall survival compared to the patients with normal levels." (PMID 33886813, 2021). "We next investigated if the JNK/c-Jun pathway regulated EGFR signalling in cervical cancer cells." (PMID 33303976, 2021). "Moreover, a recent study found that HPV E6 induces JNK phosphorylation via the PDZ-binding motif, activating c-jun expression, thereby promoting proliferation and expression of viral oncoproteins through EGFR in cervical cancer." (PMID 33668730, 2021). "Furthermore, uPA expression can have a direct impact on cervical cancer cell function, specifically EGFR-dependent cell morphology modifications and EGFR-independent cell migration." (PMID 33886813, 2021). "In conclusion, we showed that EGFR signaling regulated expression of the fibrinolytic system component uPA in both in vitro and in vivo settings, while uPA also participated in cell-morphology modifications and migration in a human cervical cancer model." (PMID 33886813, 2021). "In this study, five different genomic regions within the top three most frequently mutated genes (EGFR, KRAS and PIK3CA) in COSMIC database with a key role in the development of cervical cancers were selected to study the mutation frequency in Bangladeshi patients." (PMID 33736612, 2021). "Finally, combined PAFR and EGFR targeting treatment impaired clonogenic capacity and viability of aggressive cervical cancer cells more strongly than each treatment separately." (PMID 33392068, 2020). "HPV infection and the EGFR pathway have been identified as targets for cervical cancer therapy." (PMID 32850421, 2020). "In the current study, strong positive correlations between EGFR × PAFR, and EGFR × LPCAT2 in cervical cancer samples were shown, which led to the hypothesis that EGFR can regulate the expression of these genes involved in the biosynthesis and signaling of PAF." (PMID 33392068, 2020). "Collectively, these findings suggest that EGFR inhibitors may improve the efficacy of radiotherapy in cervical cancer." (PMID 32850421, 2020). "Incessant EGFR activation by NHERF-1 correlates with poor prognosis in cervical cancer." (PMID 32695664, 2020). "Therefore, in cervical cancer, we studied EGFR and its downstream signal transduction pathway, namely PI3K/AKT pathway." (PMID 32308562, 2020). "In the present study, to investigate the combined effect of nimotuzumab-mediated EGFR blockade and radiotherapy on E6-promoted cervical cancer growth, we established an HPV-E6–overexpressing C33A cervical squamous cell line and a nude mouse model bearing these cells." (PMID 32850421, 2020). "Moreover, in vitro data link loss of NHERF-1 in cervical cancer with increase in cellular growth, proliferation, cell cycle, and ERK signaling stimulated by EGFR." (PMID 32695664, 2020).
cervical carcinoma (continued). "GW627368X (a highly selective EP4 antagonist) inhibits the proliferation and angiogenesis of cervical carcinoma by blocking EP4/epidermal growth factor receptor (EGFR) signaling pathway in cervical cancer cell lines (HeLa, SiHa and ME180) and suppresses the tumor size in xenograft mice model." (PMID 32488496, 2020). "The epidermal growth factor receptor (EGFR) may be a biomarker in cervical cancer because of its high expression ranging between 60–90%; and in some studies, has even been affiliated with lack of prognosis." (PMID 32148661, 2019). "To explore a potential relationship between the expression of EGFR and the clinical outcome of cervical cancer patients, we mined TCGA data sets, and found that the expression of EGFR had little if any correlation with the disease-free survival of cervical cancer patients." (PMID 31772161, 2019). "Moreover, we found that the EGFR pathway was involved in YAP1-induced cervical cancer cell proliferation and migration." (PMID 30840887, 2019). "However, this inhibitor has been shown to be poorly specific for JAK kinases, with off target effects including the inhibition of EGFR, a known oncogene in cervical cancer." (PMID 31817106, 2019). "The existence of this Hippo/YAP and EGFR feedback loop in human cervical cancer suggested that the combined targeting of the Hippo/YAP and EGFR pathways may be an efficient way to treat cervical cancer." (PMID 30840887, 2019). "Research is now closing in on novel molecular targets for cervical cancer therapeutics, including the utilization of epidermal growth factor receptor (EGFR) antagonists, such as panitumumab, and multitargeted tyrosine kinase inhibitors, such as imatinib and sunitinib." (PMID 30546351, 2018). "To directly test whether EGFR modulates TF expression in cervical cancer, we treated CASKI cells with cetuximab one hour before recombinant epidermal growth factor (EGF)." (PMID 30093972, 2018). "Other studies reported that the activated YAP and EGFR signaling could form a positive signaling loop to drive cancer progression in several cell types, including cervical cancer, esophageal cancer and breast epithelial cells." (PMID 29449645, 2018). "Apart from EGFR signaling, nuclear factor-kappa B (NF-κB) is a crucial transcription factor that has an ability to activate the large array of inflammatory mediators and has been recognized as a central player for cervical cancer." (PMID 29977314, 2018). "Our results demonstrate that PAR2 transactivates EGFR in cervical cancer cells." (PMID 30093972, 2018). "Here, we report that tobacco smoke induces p97 promoter activation in CaSki (HPV16, 500 copies/cell) and SiHa (HPV16, 2 copies/cell) cervical cancer-derived cells and this activation involves EGFR activation and c-Jun phosphorylation which in turn, is recruited to TRE sites on the HPV16 LCR." (PMID 30619121, 2018). "Therefore, our results suggest that EGFR upregulates TF expression in vitro and in malignant tissues derived from cervical cancer." (PMID 30093972, 2018). "Consistent with our in vitro results, we found a significant positive correlation between the mRNA expression levels of EGFR and TF in transcriptome data from cervical cancer patients deposited in The Cancer Genome Atlas - TCGA (Spearman’s r = 0.206, P = 0.0003)." (PMID 30093972, 2018). "Mechanistically, YAP expression is correlated with human papillomavirus (HPV) integration status and is required for the upregulation of TGF-alpha, amphiregulin (AREG), and EGFR, thereby forming a positive signaling loop to drive cervical cancer cell proliferation." (PMID 30344797, 2018). "Thus, EGFR transactivation induced by PAR2 agonists contributes to ERK activation in cervical cancer cells." (PMID 30093972, 2018). "In cervical cancer cells, previous study showed that propofol could enhance cisplatin-induced apoptosis via EGFR/JAK2/STAT3 pathway." (PMID 28542400, 2017).
cervical carcinoma (continued). "It is estimated that 90% of cervical carcinomas overexpress EGFR, the same magnitude observed here." (PMID 29160417, 2017). "Indeed, previous reports have shown EGFR to be frequently expressed in cervical cancer (around 80%) and correlated with disease progression." (PMID 29160417, 2017). "In cervical cancer, EGFR, HER2, and high microvascular density correlate with survival." (PMID 30410707, 2017). "In cervical cancer, EGFR is variably expressed in 80 % of the tumor tissues." (PMID 27783105, 2017). "In our cervical cancer xenograft mouse model, co-administration of PTX with EGFR inhibitor erlotinib significantly prevented the tumor growth and relapse, which was associated with reduced expression of MUC1 and ABCB1, and diminished activity of EGFR." (PMID 28796259, 2017). "Moreover, it has been recently shown that EGFR overexpression independently predicts prognosis in patients with cervical cancer, which makes it a potential therapeutic target." (PMID 29212253, 2017). "Furthermore, EGFR has been validated by our group as an important therapeutic target in cervical cancer in preclinical model and in a phase II clinical trial." (PMID 29160417, 2017). "EGFR is known to activate EMT-inducing signaling pathways in cervical cancer." (PMID 27902484, 2017). "EGFR has thus been identified as a promising target for cervical cancer." (PMID 26881213, 2016). "Endocytosis and degradation of EGFR in response to stress treatment and effects of the p38 inhibitor, the Caspase-3 inhibitor and the proteasomal inhibitor in cervical cancer HeLa cells were determined using immunoblotting and immunofluorescent staining assays." (PMID 27034618, 2016). "This meta-analysis reveals that EGFR overexpression might be a predictive biomarker of reduced survival in patients with cervical cancer." (PMID 27438047, 2016). "In the cervical carcinoma, Oh and co-workers have determined the levels of EGFR in the serum of 38 patients (invasive or recurrent carcinoma (n = 26) and carcinoma in situ (CIS; n = 12)) and 38 healthy females as controls, using an enzyme-linked immunosorbent assay (ELISA)." (PMID 27104520, 2016). "Hence, because of the limitations of this meta-analysis, the value of EGFR expression as a prognostic indicator in cervical cancer should be confirmed in future well-designed prospective clinical trials." (PMID 27438047, 2016). "Therefore, we performed a systematic meta-analysis to quantify the effects of EGFR overexpression on survival in patients with cervical cancer." (PMID 27438047, 2016). "Previous EGFR IHC studies of cervical carcinomas show a wide range of expression levels (6–100%); these data may be a reflection of differences in antibody clone choices, IHC protocols, and/or in how staining was rated." (PMID 26209091, 2015). "Previous studies have demonstrated EGFR to be frequently overexpressed in primary cervical cancer." (PMID 25995714, 2015). "The study demonstrated that anti-EGFR/HGNs significantly increase the cytotoxicity of 6-MV X-rays on HeLa cells, and anti-EGFR/HGNs combined with radiotherapy may possess a large therapeutic potential in cervical cancer." (PMID 25995714, 2015). "Therefore, anti-EGFR/HGNs can increase the targeted uptake of HGNs by HeLa cells and enhance radiocytotoxic targeting of cervical cancer at megavoltage radiation energies." (PMID 25995714, 2015). "We found that AG1478 treatment resulted in scattered distribution of ME180 cells and incompletely formed spheroids, indicating that blockade of EGFR could partially disrupt cervical cancer cell–cell communication (Fig8E)." (PMID 26417066, 2015). "Thus, EGFR seems to have an important role in tumor angiogenesis and the prognostic of advanced cervical cancer." (PMID 24860830, 2014). "Therefore, KIAA1199 connects Semaphorin 3A signalling to EGFR phosphorylation and maintains high EGFR levels in cervical cancer-derived cells." (PMID 25366117, 2014).